EGFR (epidermal growth factor receptor)
Diseases named in the same sentence as EGFR in open-access papers (continued):
Sharing a sentence is not in itself a finding about the gene and the disease.
tumor (continued). "Approximately 10–40% of NSCLC patients worldwide have tumor cells carrying epidermal growth factor receptor (EGFR) activating mutations." (PMID 36386893, 2022). "GPR124 functions as an angiogenesis regulator, and abnormal tumor angiogenesis have been associated with anti-EGFR therapeutic resistance." (PMID 35264191, 2022). "Together, these indicated that silencing Fbxo45 played additive effects with Afatinib on suppressing the tumor growth of H1975 cells, even though harboring EGFR‐T790M resistance mutation and KRAS mutation, in vitro and in vivo." (PMID 35838331, 2022). "Nearly half of those also harbored one of the EGFR resistant mutations, suggesting possible tumor progression on 1st or 2nd-generation EGFR TKI before sample acquisition." (PMID 35566609, 2022). "It is unclear if EGFR mutations down-regulate B7-H3 expression to favor tumor immune escape in this context." (PMID 35590371, 2022). "The impact of mutational status on tumor-to-lung contrast and whole-body distribution can be investigated by the use of affinity constants for EGFR wild-type and mutated EGFR." (PMID 35890095, 2022). "On the other hand, out of the four patients with EGFR mutated tumors, only the tumor showing the highest iGenSig score exhibited an objective response." (PMID 35618721, 2022). "EGFR mutation in the primary cancer was associated with a lower PD-L1 expression, T-cell infiltration, and a tumor mutation burden." (PMID 36230886, 2022). "Analysis of circulating cell-free tumor DNA (ctDNA) is considered to be another emerging method for assessing EGFR mutation status." (PMID 35800046, 2022). "EMT is generally associated with resistance to Cetuximab and EGFR-mediated EMT promotes tumor invasion." (PMID 36076232, 2022). "Strikingly, PEAC identified EGFR L861Q mutation 6 months after surgery, which was previously detected in the tumor tissue sample, and 2 months later the patient was found tumor relapsed by MR examination." (PMID 35308511, 2022). "Therapeutic antibodies targeting tumor-associated antigens, such as Cetuximab targeting the epidermal growth factor receptor (EGFR) and Rituximab targeting CD20." (PMID 36077853, 2022). "A striking response was found in a subset of ~10–40% of patients who harboured NSCLC tumours driven by somatic activating mutations in the first 4 exons of the tyrosine kinase domain of the EGFR gene." (PMID 35158954, 2022). "Among the 837 EGFR-mutant tumor samples, 633 (75.6%) harbored classical EGFR mutations, including Ex19del (32.4%, n = 271), L858R (27.2%, n = 228), Ex19del/L858R concomitant with T790M (15.5%, n = 130), and T790M alone (0.5%, n = 4)." (PMID 36615035, 2022). "Major scientific and clinical studies have proved that alleles of patients with NSCLC revealed mutations in KRAS and EGFR genes, which demonstrate their function in tumor development and progression." (PMID 35402265, 2022). "Pre-treatment EGFR T790M mutation found in baseline tumor tissues of 28 patients (20.4%; 28/137) was significantly associated with brain metastasis (p = 0.005) and a shorter brain metastasis-free survival (p = 0.001)." (PMID 36232650, 2022). "EGFR-mutational profile of CTCs detected by CCM-CTCD correlated well with the profile of circulating tumor DNA (ctDNA)." (PMID 35664056, 2022). "Mutation in EGFR and overexpression of EGFR protein leads to the dysregulation of signals that favor tumor cells in terms of proliferation, survival, and metastasis." (PMID 36699049, 2022). "Given that PD-L1 expression in tumor tissue is an important biomarker that predicts clinical outcomes to anti–PD-1/PD-L1 treatment, it is possible that tumor tissue in EGFR-mutated NSCLC expresses low levels of PD-L1." (PMID 35132961, 2022). "For example, clinical factors such as age, sex, smoking status, tumor stage, and predominant subtype were used to build prediction models for EGFR mutation status." (PMID 36119545, 2022).
tumor (continued). "Mutation testing of RAS (KRAS and NRAS) in tumour tissue has been routinely used for several years to identify patients with advanced CRC who are intrinsically resistant to anti-EGFR antibodies (cetuximab, panitumumab)." (PMID 35055414, 2022). "PD-L1 expression levels were significantly associated with SUVmax (p = 0.001), tumor size (p = 0.022), and EGFR mutation status (p = 0.045)." (PMID 35646945, 2022). "DNA from these 33 EGFR-TKI naïve NSCLC patients was first evaluated for tumor content by determining the VAF of the EGFR driver mutation (E19 del and L858R) by ddPCR." (PMID 35884570, 2022). "The EGFR signaling pathway is associated with angiogenesis, progression, metastasis and apoptosis of the tumor." (PMID 35120180, 2022). "The TME plays a key role in regulating tumor progression and significantly affects the efficiency of immune response in patients with mutated EGFR." (PMID 35742933, 2022). "To determine if the strong statistical association of EGFR-AMPK activity in patient tumor tissue reflects a functional relationship, we stimulated GBM cells with EGF or overexpressed EGFRvIII." (PMID 36130485, 2022). "Currently, definitive diagnosis of EGFR mutation status is mainly detected from genomic DNA samples obtained from tumor tissues." (PMID 35422977, 2022). "Targeting VEGFR2, the VEGFA receptor that is essential for endothelial cell functions associated with angiogenesis, enhances the anti-tumor activity of EGFR-TKIs in NSCLC with EGFR-TKI resistance." (PMID 36304306, 2022). "For 11C-osimertinib in EGFR mutations positive tumors and for 18F-afatinib in EGFR wild type tumor, contrast values stay within the noise range." (PMID 35453931, 2022). "The progression of tumor heterogeneity via genetic and non‐genetic mechanisms was associated with osimertinib sensitivity in tumors with acquired resistance harboring EGFR‐T790M mutation." (PMID 35029047, 2022). "Accordingly, resistance to EGFR inhibitors can be associated with increased levels of VEGF in the tumor microenvironment." (PMID 35912170, 2022). "Multi-site gene mutations lead to the complexity of tumor signal transduction, which explains the use of EGFR monoclonal antibodies in the treatment of CRC patients." (PMID 36034798, 2022). "OncomineTM Dx Target Test Multi-CDx system (Thermo Fisher Scientific, USA) revealed that tumor cells harbored an identical EGFR mutation (deletion E746-A750 in exon 19) with a secondary EGFR T790M mutation." (PMID 35960133, 2022). "In conclusion, EGFR mutation models constructed from serum tumor markers and CT features have good predictive efficacy." (PMID 35422977, 2022). "Our model was a comprehensive one, including factors from clinical (age and metastases) to laboratory findings (EGFR mutation and tumor markers)." (PMID 36572759, 2022). "Around 10% of EGFR-mutated tumours contain rare somatic mutations, which are more or less evenly distributed among the affected exons (18, 19, 20, and 21)." (PMID 35454856, 2022). "Somatic mutation analysis of this cohort echoed a well-known fact that patients with the epidermal growth factor receptor (EGFR) mutations in the tumor account for 85% of the total patient population which comprises predominantly nonsmokers (83%)." (PMID 35806042, 2022). "Except for a lower percentage of poor cell differentiation in the EGFR mutation group (p < 0.001), all tumor characteristics were identical between the two groups." (PMID 36011604, 2022). "Selection of a tumor cell clone with the T790M mutation is the most common cause of resistance to first- and second-generation of EGFR TKIs." (PMID 35522668, 2022). "Comparing with cells harbouring sole KRAS or PI3K mutation, EGFR mutation can act on multiple signalling pathways in concert to well protect tumour cells from apoptosis." (PMID 35692096, 2022).
tumor (continued). "We, therefore, tested a drug library on the three tumor organoid models that contained small molecules against a wide range of cancer‐associated pathways, that is, EGFR, MAPK, BTK, and PI3K/mTOR." (PMID 35993110, 2022). "One approach to avoid EGFR-associated on-target/off-tumor toxicity is to target the EGFR variant III (EGFRvIII), which is selectively expressed in cancers, such as malignant glioblastoma." (PMID 36555466, 2022). "Overall, strong concordance (70–90%) is found between the presence of EGFR activating mutations in tumour tissue and matching ctDNA." (PMID 35055414, 2022). "We analyzed several genes associated with tumor growth and its resistance to treatment, including Bcl-2, Bax, Caspase-3, Survivin, EGFR, and VEGF." (PMID 35578215, 2022). "De novo KRAS mutations reduce the sensitivity of colorectal cells to EGFR‐targeted therapy and CRC tumours also develop resistance to anti‐EGFR therapy by acquiring mutations in RAS." (PMID 34856074, 2022). "Although tumor tissue analysis by IHC remains the gold standard for most clinical molecular analysis for targeted therapy selection (with the exception of NGS for EGFR, BRAF or NTRK gene variants), it faces several biological and technological challenges." (PMID 35714131, 2022). "The possible mechanism is that EGFR mutation is related to inhibiting the tumor microenvironment and reducing the tumor mutation burden." (PMID 35831785, 2022). "We also evaluated the anti-tumor effects of a novel treatment strategy involving the co-administration of Fasudil and an EGFR-TKI (gefitinib) in gefitinib-resistant EGFR-mutation NSCLC using in vivo and vitro models." (PMID 36230634, 2022). "High FDG avidity in the primary tumor was associated with a very low chance of harboring an EGFR mutation." (PMID 36276079, 2022). "As suggested in these studies, a possible association between the S1P and EGFR signalling pathways was associated with greater tumour invasiveness and poor prognosis." (PMID 35806446, 2022). "We found that miR-4429 was associated with tumor size (p = 0.033), EGFR mutation (p = 0.006), lymph node metastasis (p = 0.013) and TNM stage (p = 0.002) in NSCLC patients." (PMID 35167433, 2022). "Further, the inclusion of Ki‐67, EGFR mutation, and tumor differentiation greatly increased the predictive accuracy for solid components (0.962 in the training set and 0.942 in the validation set)." (PMID 35289087, 2022). "The gold standard assessment of EGFR mutation status is based on tumor tissue acquired by fine-needle aspiration, biopsy, or resection." (PMID 36276079, 2022). "ABT-806 is a humanized antibody that selectively binds an epitope only rendered accessible in tumours with the EGFRvIII mutation or wild type EGFR amplification and thought to represent 45–50% of all adult GBM." (PMID 36046842, 2022). "On the basis of preclinical data revealing antitumor activity for ICIs in EGFR-mutated tumor models, there was enthusiasm that this would translate into a clinical benefit for this group of patients." (PMID 36426286, 2022). "Mice treated with aPD-1 alone showed no treatment response, underlining the limited efficacy of ICB in EGFR-driven tumours." (PMID 36010935, 2022). "High STING tumor expression correlates with improved survival, early‐stage disease, and EGFR and KRAS mutations." (PMID 35099823, 2022). "In brief, never-smoking NSCLC patients often present with high EGFR mutation status, and patients with NSCLC harboring EGFR mutations usually show low SUVmax of the primary tumor." (PMID 35497180, 2022). "Compared with wild-type tumors, tumors with epidermal growth factor receptor (EGFR) mutations have greater heterogeneity in immune microenvironment characteristics such as programmed cell death ligand 1 (PD-L1) and tumor mutational burden (TMB)." (PMID 36172732, 2022).
tumor (continued). "GINS3, a KRAS-inactivated subtype, was featured by high tumor purity, immune-desert, activation of EGFR and ephrin receptors, CIN, fewer KRAS mutations, and SMOC1 methylation." (PMID 36345721, 2022). "These activating mutations hyperactivate the kinase activity of EGFR to stimulate oncogenic signaling that promotes tumor cell survival, proliferation, differentiation, and migration." (PMID 34675407, 2022). "A genetic analysis of the primary tumor using the Oncomine Dx target test multi-CDx system revealed positivity for EGFR (L858R and E709X) and CTNNB1 mutations." (PMID 36519636, 2022). "By combining the shared frequency and binding affinity to identify tumor specific somatic mutations, our data revealed that EGFR L858R was the top neoantigen producing gene allele, and most of these neoantigens were predicted to bind to A*33:03." (PMID 36505399, 2022). "And the presence of EGFR amplification was associated with larger tumor size, higher TNM stage, high‐grade‐component predominance and VPI." (PMID 35023616, 2022). "Recently, circulating tumor DNA (ctDNA) analysis revealed that BLU-945 achieved a median 48% reduction in EGFR resistance mutations (T790M and C797S), which represented emerging evidence of the efficacy of BLU-945." (PMID 36482474, 2022). "Tumor-restricted variants of EGFR such as EGFR variant III (EGFRvIII) can be utilized in case of safety concerns regarding the expression of EGFR on normal tissues." (PMID 36483567, 2022). "The microdissected tissues positive for EGFR exon 19 deletion (a driver gene mutation of EGFR-TKI) was scattered in the same tumor site." (PMID 36505794, 2022). "There is evidence to suggest that overexpression of the EGFR protein can be triggered by either gene mutation or by tumour hypoxia, which is one of the common traits in the tumour microenvironment." (PMID 35681586, 2022). "PD-L1 expression was significantly associated with SUVmax (p = 0.001), tumor size (p = 0.022), and EGFR mutation status." (PMID 35646945, 2022). "Approximately 40–50% of GBMs carry EGFR amplifications; among EGFR-amplified GBMs, in 20–50% of cases, a splice variant which creates a mutant form of EGFR (EGFR vIII) is present, conferring a more aggressive tumor biology." (PMID 36551961, 2022). "The objective is to determine if a complex model combining serum tumor makers and computed tomographic (CT) features can predict epidermal growth factor receptor (EGFR) mutation with higher accuracy." (PMID 35422977, 2022). "In fact, EGFR signaling regulates numerous cellular pathways associated with tumor invasion and metastasis in preclinical models of BC." (PMID 35804889, 2022). "First, the activating EGFR mutation needs to be identified in order to use the right affinity value, thereby increasing accuracy of the prediction of tumor uptake." (PMID 35890095, 2022). "For example, EGFR gene mutations in exons 18–21 detected in cfDNA or tumour cells from metastatic sites confirm NSCLC diagnosis with the same probability as pathological examination." (PMID 35884492, 2022). "Among the 10 patients who underwent both tumor and liquid biopsy at PD, the same EGFR mutations were detected in four patients by both methods (40.0%)." (PMID 36192767, 2022). "EGFR overexpression in OC has been associated with high tumor grade and poor prognosis in some studies, yet the response to EGFR targeted therapies seems limited." (PMID 35212471, 2022). "With cobas test, 40 cases (46%) showed the same activating EGFR mutation, which was previously detected in the primary tumor and T790M mutation was present in 14 out of these cases." (PMID 36277960, 2022). "Initial studies implicated the Epidermal Growth Factor Receptor (EGFR or ErbB1) in UM tumour proliferation and metastasis." (PMID 35781872, 2022). "Although serum tumor markers and CT features show values in evaluating EGFR mutation status, the accuracy of these two methods by themselves is low." (PMID 35422977, 2022).
tumor (continued). "The number of patients with matched EGFR mutations detected in CSF to the primary tumor were 9/11, 9/10, 3/5, 7/9, 21/29, 5/5, and 7/11, respectively." (PMID 36000927, 2022). "A higher proportion of patients with mutated EGFR had a tumor size of less than 30 mm (60.4% vs. 43.6%, p < 0.001) and earlier stages (p < 0.001)." (PMID 36457515, 2022). "We previously showed that RAS, BRAF and EGFR mutant alleles, which appear in circulating tumor DNA (ctDNA) during EGFR blockade, decline upon therapy withdrawal." (PMID 35915157, 2022). "EGFR is increasingly considered a biomarker of tumor drug resistance, and its amplification or secondary mutation occurs under the pressure of drugs." (PMID 36060002, 2022). "Studies in human tumor cell lines have previously shown that the tumor-associated overexpression of EGFR results in the sustained hyperactivation of Stat3, which eventually induces Smad7 expression." (PMID 36291778, 2022). "Key oncogenetic EGFR alterations upon which NSCLC tumours become addicted to EGFR signals include somatic mutations in the EGFR gene clustered around the periphery of the catalytic adenosine triphosphate (ATP)-binding cleft in EGFR’s kinase domain." (PMID 35158954, 2022). "Our results suggest the association between the radiological severity score of LM, CSF tumor cell counts, and EGFR mutation detection rate in CSF." (PMID 35740489, 2022). "In conclusion, smoking status and the factors reflecting tumor burden were associated with the detection of plasma EGFR mutation." (PMID 35207417, 2022). "Larger tumor size and presence of EGFR/ALK mutation were predictive of higher rates of starting/changing systemic therapy on multivariate analysis." (PMID 35323340, 2022). "EGFR overexpression, maturation of CAFs, and infiltrating tumor growth configurations conducting to potential tumor were associated to well-connected islands." (PMID 35454852, 2022). "Diagnosis through next-generation sequencing of tumor DNA, obtained through a histological biopsy, is the gold standard for identifying tumor EGFR mutations." (PMID 36313723, 2022). "EGFR c.2156G>C (p.G719A) and c.2497T>G (p.L833V) mutations were identified in both tissue and plasma circulating tumor DNA." (PMID 35984165, 2022). "EGFR mutations were observed in 46.9% of tumor samples of younger (n=15) and in 43.3% of samples of older patients with NSCLC (n=13) (P= 0.8039)." (PMID 36263208, 2022). "Currently, EGFR mutation status is established based on tumor tissue acquired by biopsy or resection, so there is a compelling need to develop non-invasive, rapid, and accurate gene mutation detection methods." (PMID 36276079, 2022). "In this study, we characterized the landscape of the TCRβ repertoire in tumor tissue from patients with stage II/III NSCLC with an EGFR mutation who received adjuvant therapy, including the TKI gefitinib and VP in the clinical trial." (PMID 35014626, 2022). "Newly acquired MET D1228H mutations and EGFR amplificated were detected in patient-resistant tumor specimens." (PMID 36338758, 2022). "We also previously reported that EVs isolated from bronchoalveolar lavage fluid (BALF) of patients with NSCLC contain abundant double-stranded DNA and both the detection and concordance rate of EGFR mutations using BALF-EVs increase with tumor stages." (PMID 35681723, 2022). "After allowing 18 days for tumor implantation, all mice formed palpable tumors and were injected with 10 million hinge variant EGFR-sdCAR-T cells or untransduced CAR-T cells." (PMID 35935988, 2022). "Given that PD-L1 expression in tumor tissue is an important biomarker that predicts clinical outcomes of the anti-PD-1/PD-L1 treatment, it is possible that tumors in EGFR-mutated NSCLC express low levels of PD-L1." (PMID 35742933, 2022). "A patient’s tumor expressed multiple mutations in several instances; in particular, co-mutations were observed in the uncommon sensitizing EGFR mutations." (PMID 36661661, 2022).